SEMA4A (semaphorin 4A)
Diseases named in the same sentence as SEMA4A in open-access papers (continued):
Sharing a sentence is not in itself a finding about the gene and the disease.
retinal degeneration (3 papers, 2008 to 2024). Degeneration of the retina. "Detailed examination of the underlying pathologic mechanism of retinal degeneration has shown that Sema4A deficiency led to a disruption of the rod and cone photoreceptor function." (PMID 30134791, 2018). "In addition to these roles in immune reactions, mice with a point mutation in Sema4A develop retinal degeneration, suggesting that Sema4A is also crucial for peripheral tissue homeostasis." (PMID 39737847, 2024). "At the age of 14 weeks, Sema4A−/− mice have been shown to develop severe retinal degeneration with attenuated retinal vessels and depigmentation." (PMID 30134791, 2018). "The approach identified genes that cause retinal degeneration (CNGB1, SEMA4A, RRG4) or developmental changes (SOX2) when mutated." (PMID 18334927, 2008).
cervical cancer (2 papers, 2021 to 2022). A primary or metastatic malignant neoplasm involving the cervix. "Thus, our study provides a rationale to assess SEMA4A expression on GC TIL-Bs and in TLS of other virally induced cancers such as HCC, MCC, and cervical cancer where SEMA4A expression on GC TIL-Bs has not yet been reported." (PMID 34099645, 2021).
cone-rod dystrophy (2 papers, 2008 to 2022). Inherited retinal dystrophies that belong to the group of pigmentary retinopathies. "Mutations of a semaphorin-encoded gene, SEMA4A was identified in a group of RP patients and cone-rod dystrophy (CRD)." (PMID 36274523, 2022). "Mutations of SEMA4A were found in RP35 (OMIM 610282) and in dominant cone-rod dystrophy (CRD; listed in RISN), SEMA4A is ischemia regulated in the brain." (PMID 18334927, 2008).
prostate carcinoma (2 papers, 2023 to 2024). A carcinoma that arises from epithelial cells of the prostate gland. "In this study, we found that SEMA4A was highly expressed in prostate cancer (PCa) tissues and correlated with Gleason scores and distant metastasis." (PMID 37779872, 2023).
psoriasis (2 papers, 2024 to 2026). An autoimmune condition characterized by red, well-delineated plaques with silvery scales that are usually on the extensor surfaces and scalp. "Serum Sema4A levels, measured by enzyme-linked immunosorbent assay (ELISA), were comparable between Ctl and psoriasis." (PMID 39737847, 2024). "Conclusively, Sema4A-mediated signaling cascades can be triggers for psoriasis and targets in the treatment and prevention of psoriasis." (PMID 39737847, 2024). "While Sema4A expression on blood immune cells was upregulated in psoriasis, its serum levels were comparable between Ctl and psoriasis." (PMID 39737847, 2024). "Herein, we investigated the roles of Sema4A in the pathogenesis of psoriasis by analyzing skin and blood specimens from psoriatic subjects and using a murine model." (PMID 39737847, 2024). "Immunohistochemistry of Ctl and psoriasis demonstrated Sema4A expression in keratinocytes." (PMID 39737847, 2024). "Thus, targeting the downregulated Sema4A and upregulated mTOR signaling in psoriatic epidermis can be a promising strategy for psoriasis therapy and modification of psoriatic diathesis in NL for the prevention of disease development." (PMID 39737847, 2024). "Imiquimod (IMQ)-induced psoriasis-like dermatitis is augmented in Sema4A knockout (KO) mice." (PMID 39737847, 2024). "Next, we investigated whether intraperitoneal rapamycin treatment effectively downregulates inflammation in the IMQ-induced murine model of psoriasis in Sema4A KO mice." (PMID 39737847, 2024). "Sema4A in keratinocytes may play a role in preventing murine psoriasis-like dermatitis." (PMID 39737847, 2024). "In contrast, the proportions of Sema4A-positive cells were significantly higher in blood CD4 and CD8 T cells, and monocytes in psoriasis compared to Ctl." (PMID 39737847, 2024). "On the other hand, focusing on IL-17A-producing cells, the proportion of IL-17A-producing Vγ2 and DNγδ T cells in CD3 fraction in the epidermis was significantly higher in Sema4A KO mice, consistent with the results from IMQ-induced psoriasis-like dermatitis." (PMID 39737847, 2024). "When psoriasis-like dermatitis was induced in wild-type (WT) mice and Sema4A knockout (KO) mice by imiquimod (IMQ) application on ears, ear swelling on day 4 was more pronounced in Sema4A KO mice with upregulated Il17a gene expression." (PMID 39737847, 2024). "Although we showed that downregulation of Sema4A is related to the abnormal cytokeratin expression observed in psoriasis, we could not determine the relationships between Sema4A expression and the essential molecules upregulated in psoriatic keratinocytes." (PMID 39737847, 2024).
retinal dystrophies (2 papers, 2025). "Indeed, 14 genes that are differentially bound by PRPF8Y2334N in RPE cells have been associated with various retinal dystrophies and four genes (MVK, PDSS1, MERTK and SEMA4A) are involved in RP." (PMID 40045025, 2025). "Of these patients, seven had monoallelic pathogenic variants in ABCA4, one had biallelic variants of uncertain significance (VUS) in ABCA4, two had monoallelic VUS in ABCA4, and eight harbored VUS in other retinal dystrophy-related genes, including KCNV2, RIMS1, CRB1, CFH, RP1L1, UNC119, and SEMA4A." (PMID 41234456, 2025).
retinitis pigmentosa (2 papers, 2014). Retinitis pigmentosa (RP) is an inherited retinal dystrophy leading to progressive loss of the photoreceptors and retinal pigment epithelium and resulting in blindness usually after several decades. "Furthermore, disease alleles were observed for other autosomal dominantly inherited degenerative diseases of sensory function, including retinitis pigmentosa (SEMA4A, RP1), deafness (MYO1A), glaucoma (CYP1B1, OPTN, WDR36), and keratoconus (VSX1)." (PMID 25333069, 2014).
Arthritis (1 paper, 2015). Inflammation of a joint. "One such pathway includes semaphorin 4A as reported in a recent article in Arthritis Research & Therapy." (PMID 26542940, 2015).
atherosclerosis (1 paper, 2018). A disease characterized by the build-up of fatty material and calcium deposition in the arterial wall resulting in partial or complete occlusion of the arterial lumen. "Like Sema4A, Sema4D, Sema3A, and Sema7A, reported to participate in atherosclerosis, are also widely investigated in immune cells." (PMID 30405423, 2018). "However, there is no report on whether Sema4A participates in atherosclerosis." (PMID 30405423, 2018).
Atrophy (1 paper, 2026). Any weakening or degeneration, especially through lack of use. "Subsequently, adeno-associated virus (AAV)-mediated Sema4A restoration was employed to evaluate its therapeutic potential in both dexamethasone-induced atrophy and acute injury mouse models." (PMID 42216457, 2026).
B-cell lymphoma (1 paper, 2025). "Strikingly, all the top proteins associated with B-cell lymphoma development (sCD23, FCMR, FCRL1, FCRL3, SELL, SEMA7A and SEMA4A) were most strongly associated with CLL development, suggesting CLL was a major driver of the top protein associations observed in the grouped analysis." (PMID 40894013, 2025). "Top proteins specifically associated with non-germinal center-derived B-cell lymphoma included FCMR, SPOCK2, IGSF3 and SEMA4A." (PMID 40894013, 2025).
benign prostatic hyperplasia (1 paper, 2023). A non-cancerous nodular enlargement of the prostate gland. "The protein levels of SEMA4A were analyzed by immunohistochemistry (IHC) in a series of 93 PCa and 12 benign prostatic hyperplasia (BPH) tissues." (PMID 37779872, 2023).
bladder cancer (1 paper, 2024). "This study, on the other hand, is a preliminary investigation of the potential role of sema3C and sema4A in bladder cancer." (PMID 39457718, 2024). "To the best of our knowledge, sema3C and sema4A have never been studied among patients with bladder cancer, so we are the first to report on this matter." (PMID 39457718, 2024). "Similar to sema3C, sema4A has never been studied in bladder cancer." (PMID 39457718, 2024).
cardiac ischemia (1 paper, 2024). "Interestingly, miR-218-5p has been associated with inflammation in a myocardial ischemia–reperfusion injury model, suggesting, therefore, the SEMA4A/miR-218-5p axis as a potential target for regulating cardiac inflammation." (PMID 38785931, 2024).
cerebral malaria (1 paper, 2019). A sequestration of Plasmodium falciparum in the brain, which can cause coma and/or seizures. "Previous studies by our laboratory and others have suggested that Sema4A could be a significant and direct contributor to oligodendrocyte cell loss and subsequent demyelination or white matter damage in diseases such as MS, HIV infection, neuroinflammation, and even cerebral malaria." (PMID 30736794, 2019).
clear cell renal cell carcinoma (1 paper, 2024). "Analysis of publicly available TCGA data revealed that high SEMA3A expression was associated with poorer survival in clear cell renal cell carcinoma (ccRCC), while another Semaphorin, SEMA4A was not." (PMID 38609390, 2024).
cone dystrophy (1 paper, 2024). An inherited ocular disorder characterized by the loss of cone cells, the photoreceptors responsible for both central and color vision. "Patient one had a clinical diagnosis of cone dystrophy, and the Invitae kit reported VUS in ARHGEF18, INPP5E, NPHP3, and SEMA4A; BG reported VUS in ARHGEF18 and SEMA4A." (PMID 38892829, 2024).
Crohn disease (1 paper, 2015). A gastrointestinal disorder characterized by chronic inflammation involving all layers of the intestinal wall, noncaseating granulomas affecting the intestinal wall and regional lymph nodes, and transmural fibrosis. "We aim to assess the possible involvement of semaphorin3A (sema3A) and 4A (sema4A) in peripheral immune responses and bowel tissue inflammation of patients suffering from Crohn’s disease (CD) and ulcerative colitis (UC)." (PMID 25978359, 2015).
demyelinating disease (1 paper, 2019). A broad group of disorders that affect the myelin sheaths that cover the neurons. "We previously demonstrated that Sema4A in the CSF of persons with demyelinating disease is biologically active, causing oligodendrocyte cell death." (PMID 30736794, 2019). "Taken together, our data further establish Sema4A as a potentially significant mediator of demyelinating diseases and a direct connection between the immune system and oligodendrocytes." (PMID 30736794, 2019). "Overall, the data presented in this study further illustrate a role for Sema4A-oligodendrocyte interaction in the etiology of demyelinating diseases by showing direct, adverse in vivo effects of the protein on oligodendrocytes and myelin homeostasis." (PMID 30736794, 2019). "Translation of our Sema4A-related in vitro findings of oligodendrocyte cytotoxicity to an in vivo model is a crucial step forward in establishing Sema4A as a potentially important factor involved in the pathogenesis of demyelinating diseases." (PMID 30736794, 2019). "The degree of contribution of Sema4A produced by trafficking immune cells and/or resident cells in the brain, such as microglia, to the pathogenesis of demyelinating disorders requires further study." (PMID 30736794, 2019). "In a demyelinating disease state, the Sema4A CSF concentration may range from 50 ng/mL to as high as 120 ng/mL." (PMID 30736794, 2019). "Using a Sema4A-specific ELISA, we determined that Sema4A levels are higher in individuals with HIV infection (53.72 ± 14.37 ng/mL) compared with HIV-seronegative, control individuals without known demyelinating disease." (PMID 30736794, 2019).
demyelinating disease of the CNS (1 paper, 2019). "In MS, the prototypical demyelinating disease of the CNS, Sema4A levels have been shown to be elevated in serum." (PMID 30736794, 2019).
depression (1 paper, 2023). "By combining animal and human studies, we define the behavioral relevance of this pathway, and uncover the essential role of impaired myelination and Sema4a signaling in depression." (PMID 37069164, 2023). "Overall, these results place the amygdalo-cingulate pathway at the core of pain and depression comorbidity, and unravel the role of Sema4a and impaired myelination in mood control." (PMID 37069164, 2023).
dermatitis (1 paper, 2024). An inflammatory process affecting the skin. "Imiquimod application induced more severe dermatitis in Sema4A knockout (KO) mice compared to wild-type (WT) mice." (PMID 39737847, 2024). "Analysis of bone marrow chimeric mice suggested that Sema4A expression in keratinocytes plays a regulatory role in imiquimod-induced dermatitis." (PMID 39737847, 2024).
diabetes (1 paper, 2024). "The interactions between periportal and pericentral hepatocytes, mediated by Fgf, Agt, Nectin1, Vtn, Sema4a, Angpt, Fn1, and Des, were lost in the livers of mice with diabetes at the late-stage." (PMID 39494341, 2024).
diaphragmatic hernia (1 paper, 2024). A congenital or acquired weakness or opening in the diaphragm which allows abdominal contents to protrude into the chest cavity; congenital diaphragmatic hernias are caused when the embryonic diaphragm fails to fuse. "Genetically determined SEMA4A elevation escalated the risk of both BC_overall and diaphragmatic hernia." (PMID 38887235, 2024).
diverticulitis (1 paper, 2015). An infection that develops in the diverticula of the intestinal tract. "We analyzed the expression pattern of the immune semaphorins—namely, sema3A and sema4A in colon biopsies taken from all IBD patients at onset of disease, from patients suffering from diverticulitis and from normal controls." (PMID 25978359, 2015). "Sema4A was highly expressed in lymphocytes of the lamina propria of CD and UC patients but absent in patients with diverticulitis or in normal individuals." (PMID 25978359, 2015).
familial colorectal cancer type X (1 paper, 2018). Hereditary nonpolyposis colorectal cancer characterized by the absence of germline mutations in DNA mismatch-repair genes. "The currently proven association of Sema4A mutation with Familial colorectal cancer type X (FCCTX) was first reported in 2014." (PMID 30598022, 2018).
inflammatory bowel disease (1 paper, 2019). A spectrum of small and large bowel inflammatory diseases of unknown etiology. "Association of surface Sema4a on Tconv cells with Nrp1 on Tregs increased Treg survival and function in vitro and was found to be required for the in vivo suppression of inflammatory bowel disease." (PMID 31120919, 2019).
Leber congenital amaurosis (1 paper, 2015). Leber congenital amaurosis (LCA) is a retinal dystrophy defined by blindness and responses to electrophysiological stimulation (Ganzfeld electroretinogram (ERG)) below threshold, associated with severe visual impairment within the first year of life. "For example, mutations in ABCA4, CRX, CERKL, PROM1, SEMA4A, GUCY2D can cause either CCRD, but also RP or Leber congenital amaurosis (LCA)." (PMID 26103963, 2015).
liver fibrosis (1 paper, 2022). "Next, we investigated the genotype frequency and allele distribution of selected SEMA3A, SEMA4A and SEMA5A SNPs and the possible association between the SNPs, NAFLD and liver fibrosis." (PMID 36551769, 2022).
lung adenocarcinoma (1 paper, 2025). A carcinoma that arises from the lung and is characterized by the presence of malignant glandular epithelial cells. "Trajectory analysis identified ERBB4, SEMA4A, GCNT2 and SOX4 as key factors in AT2 cells that may promote cell proliferation, migration, or epithelial-mesenchymal transition (EMT) during the progression of lung adenocarcinoma (LUAD)." (PMID 41415280, 2025).
lung fibrosis (1 paper, 2024). "Moreover, inhibition of SEMA4A-Plexin-D1 reduced lung fibrosis mediated by AKT (protein kinase B) signaling." (PMID 38148815, 2024).
lupus nephritis (1 paper, 2015). Glomerulonephritis in the context of systemic lupus erythematosus. "In a previous study of ours, we assessed the possible involvement of sema3A, sema4A and sema4D in contributing to or regulating glomerular inflammation in lupus nephritis." (PMID 25978359, 2015).
lymphoma (1 paper, 2018). A malignant (clonal) proliferation of B- lymphocytes or T- lymphocytes which involves the lymph nodes, bone marrow and/or extranodal sites. "Human CD4+ lymphoma H9 cells were transfected with the cDNA library and stained with an Allophycocyanin (APC)-conjugated SEMA4A-Fc protein." (PMID 29467366, 2018).
myeloma (1 paper, 2024). "SEMA4A expression is essential for normal myeloma growth in vitro, suggesting a reduced risk for antigen escape." (PMID 39095991, 2024). "We, and others, recently identified SEMA4A as a novel myeloma immunotherapeutic target using cell-surface proteomics." (PMID 39095991, 2024). "SEMA4A is expressed in other hematopoietic cells, but at a considerably lower level than in myeloma, and we did not see any cytopenias in a murine toxicity model." (PMID 39095991, 2024).
myopia (1 paper, 2018). "Among these ocular disease related or direct high myopia related genes, five genes (CSMD1, HSPG2, RPGR, SEMA4A and USH2A) have pathogenic variants in multiple patients." (PMID 30245926, 2018). "In addition to the novel mutations found in five known myopia genes (ADAMTS18, CSMD1, P3H2, RPGR, and SLC39A5), we also identified pathogenic variants in seven ocular disease genes (ABCA4, CEP290, HSPG2, PCDH15, SAG, SEMA4A, and USH2A) as novel candidate genes." (PMID 30245926, 2018).
neoplastic syndrome (1 paper, 2014). A broad classification for disorders in which the development of neoplasms typically occur in association with a characteristic set of signs or symptoms. "Here we have shown for the first time that SEMA4A germline variants predispose to a hereditary neoplastic syndrome." (PMID 25307848, 2014).
retinal disease (1 paper, 2014). "In fact, only the F350C but not the D345H variant was able to recapitulate the retinal disease phenotype of Sema4A-deficient mice in a homozygous knock-in mouse model, a genotype not described in humans yet18." (PMID 25307848, 2014).